RNU1-108P (RNA, U1 small nuclear 108, pseudogene)
Gene: Small nuclear RNA gene on chromosome 17 (58,666,537 to 58,666,697, reverse strand). Ensembl gene ENSG00000199426.
Homologues: Orthologues: chimpanzee U1 (96% identical), macaque U1 (71% identical), rabbit U1 (64% identical), guinea pig U1 (54% identical), zebrafish U1 (45% identical). Paralogues in human: RNVU1-31 (81% identical), RNU1-1 (81% identical), RNU1-2 (81% identical), RNU1-27P (81% identical), RNU1-28P (81% identical), RNU1-3 (81% identical), RNU1-4 (81% identical), RNVU1-18 (81% identical), RNVU1-29 (81% identical), U1 (81% identical), RNVU1-28 (80% identical), RNVU1-7 (80% identical), and 134 more.